ATP2A1 (ATPase sarcoplasmic/endoplasmic reticulum Ca2+ transporting 1)
Description:
Key regulator of striated muscle performance by acting as the major Ca(2+) ATPase responsible for the reuptake of cytosolic Ca(2+) into the sarcoplasmic reticulum. Catalyzes the hydrolysis of ATP coupled with the translocation of calcium from the cytosol to the sarcoplasmic reticulum lumen (By similarity). Contributes to calcium sequestration involved in muscular excitation/contraction.
Synonyms: SERCA1; ATP2A
Tractability: Small molecule: a drug acting on it is in phase 2 or 3 trials; a high-quality ligand is known; it belongs to a druggable protein family. Antibody: UniProt predicts a signal peptide or a membrane-spanning region. PROTAC: ubiquitination databases record sites on it; its protein half-life has been measured; a small molecule that binds it is known.
Target class: Enzyme; Hydrolase
Safety:
Unwanted effects reported when the protein is acted on. In parentheses: how it was acted on, where the effect was seen, and who reports it.
elevations of LDL cholesterol concentrations (source: ClinPGx)
Gene: Protein-coding gene on chromosome 16 (28,878,405 to 28,904,466, forward strand). Ensembl gene ENSG00000196296.
Subcellular location: Endoplasmic reticulum membrane; Sarcoplasmic reticulum membrane
Subcellular location (Human Protein Atlas): Endoplasmic reticulum
Pathways (Reactome):
Hemostasis: Reduction of cytosolic Ca++ levels
Muscle contraction: Ion homeostasis
Signal Transduction: Pre-NOTCH Processing in Golgi
Transport of small molecules: Ion transport by P-type ATPases
Gene Ontology:
Molecular function: calcium ion binding; P-type calcium transporter activity; protein binding; protein homodimerization activity; calcium-dependent ATPase activity; ATP binding; ATP hydrolysis activity; nucleotide binding
Biological process: apoptotic mitochondrial changes; calcium ion import; calcium ion transport; intrinsic apoptotic signaling pathway in response to endoplasmic reticulum stress; maintenance of mitochondrion location; negative regulation of endoplasmic reticulum calcium ion concentration; positive regulation of endoplasmic reticulum calcium ion concentration; positive regulation of fast-twitch skeletal muscle fiber contraction; positive regulation of mitochondrial calcium ion concentration; relaxation of skeletal muscle; response to endoplasmic reticulum stress; calcium ion import into sarcoplasmic reticulum; calcium ion transmembrane transport; intracellular calcium ion homeostasis; monoatomic ion transmembrane transport; positive regulation of ATPase-coupled calcium transmembrane transporter activity; positive regulation of calcium ion import into sarcoplasmic reticulum; positive regulation of cardiac muscle cell contraction; regulation of cardiac conduction
Cellular component: calcium channel complex; endoplasmic reticulum membrane; membrane; platelet dense tubular network membrane; sarcoplasmic reticulum; sarcoplasmic reticulum membrane; mitochondrion
Genetic constraint (gnomAD): Loss-of-function variants: 83 observed, 113.09 expected, observed/expected ratio (o/e) 0.73, 90% interval 0.61 to 0.88. The upper end of that interval is the gene's LOEUF score, 0.88, which puts it in group 3 of 6, group 1 being the genes least tolerant of losing a copy. Missense variants: 1,101 observed, 1,399.9 expected, observed/expected ratio (o/e) 0.79, 90% interval 0.75 to 0.83. Synonymous variants: 505 observed, 559.86 expected, observed/expected ratio (o/e) 0.9, 90% interval 0.84 to 0.97.
Homologues: Orthologues: chimpanzee ATP2A1 (99% identical), macaque ATP2A1 (98% identical), rat Atp2a1 (97% identical), mouse Atp2a1 (97% identical), guinea pig ATP2A1 (96% identical), dog ATP2A1 (96% identical), pig ATP2A1 (95% identical), tropical clawed frog atp2a1 (89% identical), rabbit ATP2A1 (89% identical), Drosophila melanogaster SPoCk (32% identical), Caenorhabditis elegans pmr-1 (31% identical), Caenorhabditis elegans catp-2 (23% identical), and 4 more. Paralogues in human: ATP2A2 (84% identical), ATP2A3 (76% identical), ATP2C1 (34% identical), ATP2C2 (33% identical), ATP1A2 (31% identical), ATP1A1 (30% identical), ATP1A3 (30% identical), ATP2B1 (30% identical), ATP1A4 (30% identical), ATP2B3 (30% identical), ATP2B2 (30% identical), ATP2B4 (29% identical), and 9 more.
Diseases named in the same sentence as ATP2A1 in open-access papers:
ATP2A1 is named in the same sentence as 76 diseases in open-access papers, as found by Europe PMC text mining. Sharing a sentence is not in itself a finding about the gene and the disease. The quoted sentences say what the papers report.
Brody disease (33 papers, 2009 to 2026). "Pathogenic variants in the SERCA-encoding ATP2A1 gene cause Brody disease, a rare recessive myopathy with exercise-induced muscle stiffness as the main feature." (PMID 41938373, 2026). "As Brody myopathy, it is an autosomal recessive inherited disorder caused by missense variants in the atp2a1 gene." (PMID 41206505, 2025). "The ATP2A1 gene encodes the fast-twitch skeletal muscle sarcoplasmic reticulum Ca(2+) ATPase; homozygous or compound heterozygous mutations in this gene cause Brody myopathy, characterized by exercise-induced impairment of muscle relaxation and stiffness." (PMID 39039444, 2024). "Brody Disease is an exceptionally rare, autosomal recessive myopathy attributed to the pathogenic variants in the ATP2A1, which encodes the sarcoplasmic/endoplasmic reticulum Ca (2+) ATPase type 1 protein SERCA1." (PMID 38125752, 2023). "In conclusion, our report expands the clinical and molecular features associated with ATP2A1 variants in Brody Myopathy." (PMID 37332993, 2023). "Here, we report a Turkish Brody Disease patient with a homozygous c.428G>A p.Arg143Gln (NM_004320.4) missense mutation in the ATP2A1." (PMID 38125752, 2023). "Atp2a1 plays a pivotal role in Ca2+ regulation in skeletal muscle, and Atp2a1 mutations have been linked to Brody myopathy and atrophic muscular disease." (PMID 36076959, 2022). "Even within the myopathies classified as Brody’s disease, there is a degree of heterogeneity in the ATP2A1 mutations as they have been documented in the A-, P-, and N-domains as well as several others at various points along the transmembrane helices." (PMID 36413081, 2022). "This variant was selected for further analyses since ATP2A1 is associated with Brody myopathy and is aberrantly spliced in myotonic dystrophy." (PMID 30688039, 2019). "ATP2A1 is the causative gene for pseudomyotonia in Chianina cattle, and this new bovine genetic disease is a suitable large-animal model for human Brody disease." (PMID 31770673, 2019). "This is also in close vicinity of ATP2A1, a gene involved in muscular contraction and relaxation, and a causal gene for a muscle disorder called Brody disease, which is characterized by muscle cramping after exercise." (PMID 29691431, 2018). "In humans, deficientactivity of SERCA1 because of ATP2A1 gene mutations causes a rare myopathynamed Brody disease (Refs 36, 37, 38)." (PMID 27055500, 2016). "Recessive mutations in ATP2A1 are known to cause Brody myopathy, a rare muscle disorder characterized by exercise-induced impairment of muscle relaxation and stiffness." (PMID 25614869, 2014). "DNA changes at ATP2A1 loci (e.g., whole gene deletions, single exon deletions, splice site mutations, and small exon transposition deletions or insertions), and missense substitutions can result in Brody myopathy, which is an autosomal recessive myopathy." (PMID 35692882, 2022). "Brody myopathy is the classic human disease associated with mutations in ATP2A1 to date." (PMID 30688039, 2019). "This study confirms the potential of novel in silico algorithms to detect cryptic mutations in existing NGS data; expands the phenotypic spectrum of ATP2A1 mutations beyond classic Brody myopathy; and suggests that genetic testing of ATP2A1 should be considered in patients with clinical myotonia." (PMID 30688039, 2019). "Brody’s disease originates from mutations to SERCA1 through the ATP2A1 gene." (PMID 28489021, 2017). "Mutations in the gene SERCA1 and ATP2A1 have been associated with Brody's myopathy." (PMID 22253609, 2012). "Similarly, mutations in the gene ATP2A1 (sarco(endo)plasmic reticulum calcium-ATPase 1 (SERCA1)) on chromosome 16p11 result in Brody myopathy, which is characterized by a decrease or loss of sarcoplasmic reticulum Ca2+-ATPase activity and problems with muscle contraction." (PMID 30380695, 2018). "As Brody myopathy, bovine PMT is an autosomal recessive inherited disorder caused by missense variants in the atp2a1 gene." (PMID 41206505, 2025).
Brody disease (continued). "Brody disease (BD) is an “ultra-rare” human genetic disorder of skeletal muscle function due to defects in the atp2a1 gene." (PMID 39273176, 2024). "Further investigations showed that, as in Brody myopathy and in bovine PMT, acc mutants carry various defects in the atp2a1 gene encoding SERCA1." (PMID 39273176, 2024). "Exercise-induced muscle stiffness is the hallmark of Brody disease, an autosomal recessive myopathy due to biallelic pathogenic variants in ATP2A1, encoding the sarcoplasmic/endoplasmic reticulum Ca2+ ATPase SERCA1." (PMID 37332993, 2023). "As in the case of bovine PMT, Brody disease is due to SERCA1 deficiency, resulting from defects of the ATP2A1 gene, many of which are missense mutations." (PMID 36293223, 2022). "Other genes examined in these NDM patients were CAV3, ATP2A1 (Brody disease) and HINT1 (hereditary neuromyotonia with axonal neuropathy)." (PMID 33263785, 2021). "In Chianina cattle, a missense mutation in exon 6 (c.491G > A) of the bovine ATP2A1/SERCA1 gene, was implicated in Congenital Pseudomyotonia, a disease very similar to BSP and paralleled to human Brody disease by Drögemüller and collaborators." (PMID 23782433, 2013). "The clinical manifestations, genetic patterns, and prevalence of myopathies vary in Brody myopathy and RYR1 mutation-associated myopathies, whereas an exon group analysis of a malignant hyperthermic family reported that all members of the family had ATP2A1 deletion of Brody myopathy." (PMID 35692882, 2022). "Although similar in name and presentation, Brody’s disease but not Brody’s syndrome involves a mutation in the ATP2A1 gene encoding SERCA1a." (PMID 36413081, 2022). "Bovine PMT disease strongly resembles the inherited Brody myopathy in humans, a condition of exercise-induced impairment of skeletal muscle relaxation, stiffness and cramps, caused by mutations of ATP2A1 coding for SERCA1." (PMID 23046865, 2012). "Since our affected siblings shared disease-associated mutations in RYR1 and ATP2A1, and the index case was diagnosed as MHS after postoperative rigidity, we considered the possibility that this family is affected with two different coexisting diseases, MH and Brody myopathy." (PMID 25614869, 2014). "Therefore, because ATP2A1 and RYR1 are required to temporally coordinate calcium concentration, zebrafish ryr1b mutants might provide a useful model for Brody myopathy and MmD." (PMID 19956802, 2009).
Myotonia (7 papers, 2013 to 2025). An involuntary and painless delay in the relaxation of skeletal muscle following contraction or electrical stimulation. "Thus, mutations in ATP2A1 lead to abnormalities of Ca++ transmembrane flux that help to explain the stiffness and clinical myotonia in our patient." (PMID 30688039, 2019). "ATP2A1 exon 22 exclusion is associated with muscle dysfunction, CLCN1 exon 7a inclusion is associated with myotonia, and MBNL1 exon 5 inclusion is associated with MBNL1 subcellular localization." (PMID 37111604, 2023). "Whereas some parameters like myotonia and Atp2a1 exon 22 inclusion displayed a sort of all-or-nothing effect, others exhibited a more graded correlation with transgene expression, such as miR-218 relative expression and Bin1 exon 11 inclusion." (PMID 40016516, 2025). "Notably, there are a few genes that are misspliced in DM1, and have been linked to a definitive symptomatic outcome, that are misspliced neither in FSHD nor EDMD, namely CLCN1, ATP2A1/2 and MYOM1, of which the CLCN1 missplicing results in the most unique feature of DM1: myotonia." (PMID 40149583, 2025).
muscular dystrophy (6 papers, 2013 to 2025). Muscular dystrophy (MD) refers to a group of more than 30 genetic diseases characterized by progressive weakness and degeneration of the skeletal muscles that control movement. "In mammalian models, overexpression of ATP2A1 restores calcium homeostasis and ameliorates muscular dystrophy pathology, while reduced ATP2A1 function is linked to contractile dysfunction and age-related muscle weakness." (PMID 41300837, 2025).
breast carcinoma (4 papers, 2020 to 2022). "Materials and methods: Using cBioPortal breast cancer patient data, Kaplan–Meier plots demonstrated that high ATP2A1 and ATP2A3 expression was associated with reduced patient survival." (PMID 34684111, 2021). "However, inconsistent with the findings of this study, the expression of ATP2A1 in breast cancer tissues appears to be lower than in normal tissues, which may be due to the tumour heterogeneity." (PMID 35754841, 2022). "For example, the expression level of ATP2A1 and ATP2A3 in breast cancer is significantly higher and closely related to the malignant progression of the tumor, leading to a reduction in the survival time of patients." (PMID 35783262, 2022). "Moreover, bioinformatics analysis indicated that ATP2A1 and ATP2A3 expression was highly altered in patients with breast cancer." (PMID 34684111, 2021).
cholangiocarcinoma (3 papers, 2021 to 2025). A carcinoma that arises from the intrahepatic biliary tree (intrahepatic cholangiocarcinoma) or from the junction, or adjacent to the junction, of the right and left hepatic ducts (hilar cholangiocarcinoma). "In cholangiocarcinoma, ATP2A1 is highly expressed and associated with the hyperimmune state of the tumor microenvironment." (PMID 41246353, 2025). "The expression of ATP2A1 in cholangiocarcinomas was significantly increased and correlated with the high immune state in the tumor microenvironment, which can be a high risk factor for the prognosis of patients." (PMID 35783262, 2022). "In conclusion, the results of the present study suggest that the cholangiocarcinoma (CHOL)-hub genes (SNX15, ATP2A1, PDCD10, BET1, and HMGA2) can be used as biomarkers of tumor progression, metastasis, therapy outcome, and poor prognoses of CHOL." (PMID 34831096, 2021).
colon cancer (3 papers, 2022). "We further analysed the mutation rates of ten risk genes in colon cancer patients and showed that ATP2A1 had the highest mutation rate." (PMID 35754841, 2022). "We found that the expression level of ATP2A1 was significantly increased in colorectal cancer patients and colon cancer patients." (PMID 35783262, 2022). "The knockdown of ATP2A1 expression significantly inhibited the proliferation and migration of colon cancer cell lines." (PMID 35754841, 2022). "Firstly, we explored the mRNA expression level of ATP2A1 in paracancerous and tumor groups of colorectal cancer in the TCGA dataset, as well as in normal tissues and colon cancer tissues in the GEO dataset." (PMID 35783262, 2022). "Finally, we downgraded the expression of one of the ATP2A1 one of the model gene to explore its role in colon cancer." (PMID 35754841, 2022). "Thus, we suspect that ATP2A1 may be an important molecule influencing the malignant progression of colon cancer." (PMID 35754841, 2022). "Meanwhile, targeting of ATP2A1 may become a potential therapeutic strategy for colon cancer." (PMID 35754841, 2022). "Our data suggest that ATP2A1 may promote the proliferation of colon cancer cells." (PMID 35754841, 2022). "Three different genes (ATP2A1-3) encode the Ca2+-ATPases from the Sarco/endoplasmic reticulum (SERCA) to maintain calcium homeostasis between the cell cytoplasm and the endoplasmic reticulum, and they have been reported to downregulate transcription in gastric and colon tumors." (PMID 35449571, 2022). "Dates from the TCGA database showed that CRC tissues had higher expression levels of ATP2A1 than adjacent normal tissue.K-M curves displayed that high expression of ATP2A1 is correlated with poor OS, FP and PPS of colon cancer patients." (PMID 35754841, 2022).